AQP5 (aquaporin 5)
Diseases named in the same sentence as AQP5 in open-access papers (continued):
Sharing a sentence is not in itself a finding about the gene and the disease.
lung carcinoma (27 papers, 2008 to 2025). "The proliferation capacity of lung cancer cells was shown to be favourably linked with the amount of AQP5 expression." (PMID 38336645, 2024). "AQP5 has also been intimately linked with activation of the EGFR/ERK/p38 MAPK signaling pathway in lung cancer." (PMID 30555637, 2018). "Conclusion of another experiment revealed that it is possible that the increased metastatic potential of lung cancer is caused, at least in part, by the fact that AQP5-positive cells lose epithelial cell markers and hasten EMT by stimulating c-Src through the SH3 binding domain." (PMID 38336645, 2024). "If measurements of AQP expression, particularly AQP5, which is overexpressed in lung cancer, may be reliably used as a diagnostic marker, we may be able to detect lung cancer at much earlier stages." (PMID 30555637, 2018). "Chen and colleagues utilised short hairpin RNA to inhibit the translation of the AQP5 gene; thus, the migration ability of lung cancer SPCA1 cells was significantly diminished." (PMID 38336645, 2024). "Targeting Ser156 in AQP5 is a promising therapeutic strategy due to its role in lung cancer cell growth and invasion." (PMID 38336645, 2024). "Zhang and colleagues found that lung cancer cells with elevated AQP5 activity had a greater proliferative capacity than those with low AQP5 activity." (PMID 38336645, 2024). "Patients with lung cancer who expressed AQP5 significantly had a greater rate of tumour recurrence and a shortened tumour-free survival rate." (PMID 38336645, 2024). "This article presents a review of the literature discussing the role of AQP5 in pathophysiology of lung cancer, with a special focus on lung adenocarcinoma." (PMID 36766810, 2023). "The analysis substantiates the conclusion that the prognostic value of AQP5 in lung cancer requires further research." (PMID 36766810, 2023). "AQP5 has been shown to be ectopically expressed or overexpressed in various cancers, such as breast and lung cancer, in which AQP5 expression levels correlated with poor prognosis." (PMID 36768212, 2023). "Studies on human tissues were initiated due to a potential role of AQP5 in progression of lung cancer and its involvement in EGFR signaling pathways." (PMID 36766810, 2023). "Expression of AQP1, AQP3, and AQP5 was negatively associated with the degree of cellular differentiation, and higher expressions of AQP1 and AQP5 were observed among invading lung cancer cells with metastasis." (PMID 35847914, 2022). "A later follow-up study reported that AQP1, AQP3, and AQP5 were detected in 71%, 40%, and 56% of resected lung cancers, respectively." (PMID 35847914, 2022). "Overexpression of AQP1, AQP3 and AQP5 has been the major focus of papers published in the lung cancer field." (PMID 32679804, 2020). "AQP5 has been reported with a role in invasion in lung cancer, an effect mediated at the protein level and connected with its phosphorylation." (PMID 31429720, 2019). "Ser156 in AQP5 is a potential therapeutic target due to its role in lung cancer cell proliferation and invasion." (PMID 30555637, 2018). "Lung cancer cells with high AQP5 expression had enhanced proliferation and migration potential, while cells with reduced AQP5 expression had low metastatic activity." (PMID 25767807, 2015). "To build on our findings from the colon and lung cancer models, in this report, we have studied the AQP5 expression pattern and its role in human chronic myelogenous leukemia (CML)." (PMID 18612408, 2008). "Overexpression of AQP5 may induce lung cancer cell spread and invasion by triggering the EGFR/ERK/p38 MAPK cascade." (PMID 38336645, 2024). "AQP5 expression is correlated with cell invasiveness and metastasis of human prostate cancer, lymph node metastasis in patients with colon cancer, and metastatic potential of lung cancer cells." (PMID 29922644, 2018).
lung carcinoma (continued). "Additionally, AQP5 mediates lung cancer cell membrane osmotic water permeability, and has been suggested to contribute to cancer cell migration and invasion by enabling rapid cell volume regulation and subsequent protrusion formation." (PMID 29922644, 2018). "AQP5-positive cells exhibited a loss of epithelial cell markers and activation of c-Src by AQP5 through SH3 binding domain to promote EMT, which might contribute to the enhanced metastasis potential of lung cancer." (PMID 25886458, 2015). "AQP1, AQP3, AQP4 and AQP5 are over-expressed in lung cancer." (PMID 25886458, 2015). "Over-expressed AQP5 could facilitate lung cancer cell growth and invasion through the activation of the EGFR/ERK/p38 MAPK pathway." (PMID 25886458, 2015). "Furthermore, activation of the P38 signaling pathway upregulated the expression of AQP5 in lung cancer tissue." (PMID 25009607, 2014). "First, based on immunohistochemical analysis of hAQP5 with 408 NSCLC tissues, we have investigated whether expression profile of AQP5 in human lung cancer correlates with disease progression and survival." (PMID 18478076, 2008). "In this study, we investigated the role of AQP5 in lung cancer." (PMID 18478076, 2008). "Hence, the influence of AQP5 on lung cancer prognosis calls for further research." (PMID 36766810, 2023). "Thus, decreasing the expression of AQP5 can delay the progression of lung cancer." (PMID 36766810, 2023). "Moreover, methylation analysis of the AQP5 promoter region suggested that promoter demethylation may play a role in the expression of AQP5 in head and neck and lung cancer cell lines (manuscript in preparation)." (PMID 18612408, 2008). "Overexpression assays of ten genes, including sub-cluster markers AQP5 and KPNA2, further indicated their functional roles, providing potential targets for early diagnosis and treatment in lung cancer." (PMID 35027529, 2022). "In lung cancer, overexpression of nuclear factor of activated T cells 5, also known as NFAT5, intimately interacts with AQP5, increasing AQP5 expression in order to promote cell proliferation and migration." (PMID 30555637, 2018). "AQP1 and AQP5 play important roles in lung pathophysiology and disease, including chronic and acute lung injury, COPD (COPD), other inflammatory lung diseases, and lung cancer." (PMID 37180448, 2023). "We have analyzed lung cancer tissues samples as a control and while we did not notice any degree of AQP5 gene amplification from lung cancer tissue samples, over 10 percent of small sized samples with AQP5 expression, we have confirmed gene amplification." (PMID 36706090, 2023). "In addition, we found that a high level of AQP5 showed a positive effect on OS and FP in all LUAD patients, while some researchers reported that AQP5 expression in lung cancer tissues was related to a poor prognosis." (PMID 34708074, 2021). "In lung cancer it is common to see overexpression of AQP1, AQP3, AQP4, and AQP5." (PMID 30555637, 2018). "The endothelial cell ECV-304 was used as a negative control and human lung cancer cell line A549, the AQP5-expressing cancer cell line was used as a positive control for AQP5 expression." (PMID 25217331, 2014). "The reaction without RT was used as a negative control and human lung cancer cell line A549, the AQP5-expressing cancer cell line, was used as a positive control for AQP5 expression." (PMID 22145049, 2011). "Marker gene expression indicates that the columnar cells are different from cells that were previously associated with lung cancer stem cells, BASC, or regeneration in the lung, i.e. variant clara cells because they express Aquaporin 5 and are negative for CCSP." (PMID 19551151, 2009).
dry eye (26 papers, 2011 to 2025). "Reduced levels of tear film aquaporin-5 are associated with dry eye and/or other epithelial surface pathologies." (PMID 38756167, 2024). "Our previous study found that AQP5-deficient mice have a stable dry eye phenotype and that AQP5 deficiency leads to pyroptosis in LGs by aggravating the ROS/NLRP3 inflammasome." (PMID 37707834, 2023). "In addition, AQP5 expression on conjunctival cells was significantly reduced in post-vitreo-retinal surgery, suggesting that this alteration was associated with dry eye outcome after the surgery." (PMID 34540996, 2021). "A loss of AQP5 in the lacrimal gland and corneal epithelium could theoretically lead to a reduction of the aqueous component of the tear film with consecutive aqueous deficient dry eye (ADDE)." (PMID 35847789, 2022). "In this study, we found that AQP5–/– mice naturally develop dry eye symptoms from birth, which makes them a stable, simple, and effective dry eye research animal model that can be used to study the pathogenesis of this condition." (PMID 33013441, 2020). "The AQP5 level has been considered to decrease with the occurrence of dry eye and is usually regarded as an indicator of dry eye in fundamental research." (PMID 33013441, 2020). "AQP5 highly expressed in lacrimal and salivary gland was reported to be lowered in a rabbit model of dry eye and the interaction between MUC5AC and AQP5 was pointed out." (PMID 32437405, 2020). "In the course of our routine breeding of AQP5–/– mice, we found that these mice exhibited spontaneous dry eye symptoms." (PMID 33013441, 2020). "A previous study considered AQP5 level as an index of dry eye, and the occurrence of dry eye is believed to be accompanied by a decrease in AQP5 level." (PMID 33013441, 2020). "In this study, we used aquaporin 5 knockout (AQP5–/–) mice that exhibit dry eye characteristics and performed hematoxylin–eosin staining to determine structural changes in the lacrimal glands of these mice." (PMID 33013441, 2020). "Such uncertainty exists because the tear film osmolarity measurements of most dry eye patients are lower than those needed to induce rises in HCEC AQP5 expression and proinflammatory cytokine secretion along with cell death in this study." (PMID 28680052, 2017). "The increased levels of AQP5 may directly impact tear secretion and lead to the characteristic dry eye symptoms observed in SS." (PMID 39408709, 2024). "A previous study indicated that AQP5 may be related to DED; this is because AQP5–/– mice spontaneously exhibited dry eye symptoms and because AQP5 deficiency caused structural changes in LG epithelial cells." (PMID 37108146, 2023). "We found that the phosphorylation of ERK and the expression of AQP5 were significantly elevated in the hyperosmotic-condition-induced dry eye cell model, as well as the inflammatory IL-6, IL-8 and TNF-α, which promote the inflammatory response and apoptosis of cells." (PMID 36232498, 2022). "Given that the loss of the PACAP gene in mice causes dry eye-like symptoms, such as corneal keratinization and tear reduction, PACAP eyedrops can stimulate tear secretion by increasing the water permeability of lacrimal acinar cells through aquaporin 5 (AQP5)." (PMID 36009532, 2022). "In addition, abnormal levels of AQP5 are present in tears of patients with dry eye indicating that AQP5 leaks into the lacrimal fluid from damaged cells of the lacrimal gland or the cornea." (PMID 34163358, 2021). "Thus, to better understand the complex pathogenesis of dry eye, identification of comprehensive circRNA expression profiles in the lacrimal glands of AQP5–/– mice was critical." (PMID 33013441, 2020). "Chrysotoxine isolated from D. nobile can increase the expression of AQP-5 in dry eyes, one of the symptoms of SS, and restore the distribution of AQP-5 in lacrimal glands and corneal epithelia, by inhibiting the release of cytokines, such as IL-1, IL-6, and TNF-α." (PMID 25945114, 2015).
dry eye (continued). "Our data also showed altered expressions of AQP4 and AQP5 during pregnancy and suggested that these changes may contribute to the altered LG secretion and dry eye symptoms during pregnancy." (PMID 22128232, 2011). "Therefore, ERK/AQP5 pathway plays an important role in the in vitro dry eye cell model." (PMID 36232498, 2022). "This may be because the type of dry eye after AQP5 knockout is primary." (PMID 33013441, 2020). "The fact that AQP4 and AQP5 expressions underwent significant changes during pregnancy suggests changes in their functional status which may potentially contribute to the changes of LG fluid secretion and dry eye symptoms during pregnancy." (PMID 22128232, 2011). "Experimental studies utilizing both dry eye guinea pig models and LPS-induced acute lung injury rat models have provided compelling evidence that VIP modulates AQP5 expression and macrophage M1/M2 polarization via the cAMP-PKA signaling axis." (PMID 41034926, 2025). "Specifically, immunoblotting against AQP5 and MUC5AC in the total protein homogenates isolated from the rabbit conjunctiva showed a positive and synchronous expression pattern with progressive upregulation in dry eye mice models." (PMID 36077012, 2022). "However, whether AQP5 deficiency can cause dry eye has not been proved yet." (PMID 33013441, 2020). "Development of dry eye-like symptoms such as reduced tear secretion and corneal keratinization has been reported in PACAP-null mice, which could be improved by PACAP eye drops via the PAC1R/adenylyl cyclase/cAMP/protein kinase A (PKA)/aquaporin 5 (AQP5) cascade." (PMID 34575359, 2021). "However, whether dry eye occurs because of AQP5 knockout has not been reported." (PMID 33013441, 2020). "Thus, in the absence of symptomatic dry eye postvitreo-retinal surgery, conjunctival changes in the form of reduced goblet cell density, altered MUC4, MUC16, AQP5 and cytokines are suggestive of dry eye at a molecular level and based on goblet cell density." (PMID 32437405, 2020).
colon carcinoma (23 papers, 2008 to 2025). "By using siRNA to inhibit AQP5 activity in HT 29 colon carcinoma cell lines, the susceptibility of these populations to the chemotherapeutic agents cisplatin (DDP) and 5 fluorouracil (5 FU) was enhanced." (PMID 38336645, 2024). "AQP5 is highly expressed in metastasized colon cancer tissue and was associated with cell proliferation and metastasis of colon cancer cells to the liver." (PMID 25767807, 2015). "AQP5 expression in colon cancer cell lines and human colon cancer tissues may be associated with cell proliferation and metastasis to liver." (PMID 24224160, 2013). "In particular, AQP5 expression in colon cancer cell lines and human colon cancer tissues is associated with cell proliferation and metastasis to liver, suggesting that altered expression of AQP5 could play a role in tumor progression." (PMID 22145049, 2011). "Based on our observations with clinical samples from NSCLC and also from our previous observation in colon cancer, where AQP5 expression was detected in patients with liver metastasis, we hypothesized that AQP5 is associated with cell invasion." (PMID 18478076, 2008). "AQP5 silencing decreases cell invasion by modulating EMT-related proteins in colon cancer and hepatocellular carcinoma (HCC), but also through the downregulation of Wnt/β-catenin and the nuclear factor-kappa B (NF-ĸB) signaling pathways, respectively." (PMID 39941100, 2025). "It has been shown that AQP5 silencing increases sensitivity to cisplatin and 5-FU in HT-29 colon cancer cells by inhibiting the p38 MAPK pathway and suppressing MDR genes." (PMID 40244097, 2025). "In HT-29 colon cancer cells, AQP5 has been shown to contribute to resistance to 5-fluorouracil and cisplatin, as silencing of AQP5 suppressed multidrug-resistance (MDR) genes through inhibition of the p38 mitogen-activated protein kinase (MAPK) pathway." (PMID 40244097, 2025). "In colon carcinoma cells, genetic silencing of AQP5 increased chemosensitivity and inhibited p38 MAPK pathway." (PMID 38336645, 2024). "Higher levels of expression of peroxiporins AQP1, AQP3 and AQP5 in colon cancer cell lines correlated with better protection from oxidative insults, even when the background activity of antioxidant defense system components remained unchanged." (PMID 38451099, 2024). "High AQP5 expression can enhance the level of phosphorylated SMAD2, promoting EMT in a colon cancer cell model, whereas suppressed expression of AQP5 can downregulate phosphorylated SMAD2, resulting in downregulated EMT response." (PMID 35847914, 2022). "During colorectal carcinogenesis, the expression of AQP1 and AQP5 was induced in early-stage disease (early dysplasia) and maintained through the late stages of colon cancer development." (PMID 35847914, 2022). "The over-expression of AQP5 promoted cell proliferation, while deletion of AQP5 inhibited colon cancer cell growth." (PMID 25886458, 2015). "A positive relationship between AQP5 over-expression and the number of circulating tumor cells was observed in colon cancer." (PMID 25886458, 2015). "Alternatively, in situ hybridization demonstrated that the expression of AQP5 was induced in early-stage disease (early dysplasia) and then maintained through the late stages of colon cancer development." (PMID 23148732, 2012). "In colon carcinoma cells, ablation of AQP5 may increase chemosensitivity by inhibiting the p38 MAPK signalling pathway." (PMID 38336645, 2024). "AQP5 has been demonstrated to engage with the Ras cascade in colon cancer, suggesting that these might play a greater role in communication than previously thought." (PMID 38336645, 2024). "The fact that other peroxiporins may also be contributing to the regulation of this pathway, as in glioma and colon cancer cells where AQP5 affects the EGFR/PI3K/Akt signaling pathway, cannot be disregarded." (PMID 37175840, 2023).